CCL19 (C-C motif chemokine ligand 19)
Diseases named in the same sentence as CCL19 in open-access papers (continued):
Sharing a sentence is not in itself a finding about the gene and the disease.
breast cancer (continued). "In this research, human breast cancer MCF‐7 and MDA‐MB‐231cells were treated with CCL19 and small‐interfering RNA (CCR7 siRNA) for activation and inhibition of CCR7, respectively." (PMID 28378417, 2017). "CCL-19 and -24, CXCL-1 and -10, and IL-6 were increased in dense breast tissue only, whereas IL-18BP was increased in breast cancer only." (PMID 29387062, 2017). "Utilizing a unique 3D microfluidic device, we here showed that breast cancers (MCF-7, MDA-MB-231, MDA-MB-436 and SK-BR-3)-derived soluble factors increase the migration of DCs toward CCL19." (PMID 27451948, 2016). "First, the expression of mRNA for CCR7 and its ligands CCL19 and CCL21 was confirmed in breast cancer cell lines and in malignant and normal tissues from breast cancer patients." (PMID 22251626, 2012). "Chemokines CCL19, CCL20 and CCL21 and their receptors CCR6 and CCR7, were assessed as potential biomarkers of metastatic dissemination in primary breast cancer." (PMID 21624121, 2011). "Cell motility was more asymmetric at CCL19 concentrations close to the CCR7 dynamic kinetic binding constant, suggesting that CCL19 is involved in regulating tumor cell heterogeneity and invasive ability in the breast cancer microenvironment." (PMID 37864213, 2023). "Overall, CCL19, CCL21, GPR183, P2RY13, and PENK were potential protective factors in breast cancer." (PMID 32195260, 2020). "Our analysis suggests that CCL19, CCL21 and IL7 signaling play an important role in attracting and activating immune cells in the breast cancer microenvironment and might help convert immune cold cancers to immune hot." (PMID 30967156, 2019). "In the present study, we assessed the expression of CCR6, CCR7 and their ligands CCL19, CCL20 and CCL21 using immunohistochemistry in a series of tumors prospectively collected from patients with loco-regional breast cancer treated at the Centre Léon Bérard in 1996 and 1997." (PMID 21624121, 2011). "Chemokine (C-C motif) ligand 19 (CCL19), the cognate ligand for CCR7, induced the activation of extracellular signal-regulated kinase (ERK) and AKT signaling and increased the expression of cell cycle regulatory proteins and proliferation of breast cancer cells." (PMID 24915301, 2014).
COVID-19 (25 papers, 2020 to 2025). A disease caused by infection with severe acute respiratory syndrome coronavirus 2. "However, a proteomic analysis of spleen tissue and BAL collected from patients with fatal COVID-19 showed that CCL19 expression was decreased, which was associated with decreased CD8+ T cell proportions." (PMID 35893822, 2022). "In conclusion, our work supports further clinical investigation correlating prognosis by stratifying patients based on the circulating molecules involved in complement activation shown recently, or characteristic cytokines such as CCL19, implicated in COVID-19 mortality." (PMID 35438176, 2022). "In addition, CCL19 plasma levels were significantly elevated in patients with COVID-19 and were associated with poor symptoms and acute respiratory distress syndrome (ARDS), suggesting that CCL19 plasma levels can be used as an early prediction marker of worsening symptoms of COVD-19." (PMID 35893822, 2022). "Markers found to be significantly elevated in COVID-19 compared to control samples included CCL19, CXCL-13, MCP-3, PGF, HGF and TNF." (PMID 39767799, 2024). "CCL-22 and CXCL-17, which are often raised alongside CCL-19 in COVID-19, showed little difference between the two arms." (PMID 39000027, 2024). "A decreased abundance of a cluster of several leukocyte chemotactic factors (MCP-4, CXCL12, CCL11, CCL19, CCL25, and CCL20) was observed in the COVID-19 cases and associated with a decrease in the cytotoxic T-cell marker CD8A." (PMID 34710339, 2022). "Increased CCL19 plasma levels were detected in patients with COVID-19 treated in the ICU, which correlated with a high mortality rate." (PMID 35893822, 2022). "Patients with PS or LC show persistent systemic inflammation 12 months after the acute COVID-19 episode, but CCL3 and CCL19 are specifically associated with PS, and the deterioration of DLCO in these patients, whereas LC patients present increased circulating levels of organ-damage markers." (PMID 40247373, 2025). "This may explain the increase in ITAC (CXCL11), MCP1 (CCL2) and MIP3b (CCL19) in individuals with long COVID-19 in our study, as these SIM are mainly expressed by monocytes, macrophages or dendritic cells." (PMID 39578604, 2024). "Further, the angiogenic factor PGF, correlated in one study to in-hospital mortality in COVID-19, was, along with CCL19, GAL-9 and DCN, significantly elevated in patients with severe COVID-19 in comparison to healthy controls, as in our IPF ex vivo model and in IPF serum." (PMID 39767799, 2024). "Fifteen proteins were significantly increased in the severe group in comparison to healthy controls, of which pleiotrophin (PTN), adhesion G protein-coupled receptor G1 (ADGRG1) and C-C motif chemokine ligand 19 (CCL19) were the top three proteins most elevated in patients with severe COVID-19." (PMID 39767799, 2024). "To explore the mechanisms of decreased expression of PD-1 in CD4+ and CD8+ T cells from convalescent COVID-19 patients, we measured plasma cytokines associated with PD-1 expression, including IL-2, IL-6, IL-7, IL-10, IL-12p70, IL-33, IFN-γ and CCL19/MIP-3, by Luminex." (PMID 38424104, 2024). "It is noteworthy that two patients with severe COVID-19 who died during their hospital visit exhibited additional elevated plasma levels of CCL19, placenta growth factor (PGF) and carbonic anhydrase IX (CAIX), proteins mainly involved in tissue remodeling processes." (PMID 39767799, 2024). "Thus, the chemokine antibody signature that distinguished healthy controls from COVID-19 convalescents (autoantibodies to CCL19, CCL22 and CXCL17) was different from the signature associated with COVID-19 severity (autoantibodies to CXCL5, CXCL8 and CCL25)." (PMID 36879067, 2023). "Additionally, a study that examined gene expression and serum levels revealed that CCL19 was upregulated in patients with COVID-19 relative to healthy controls, and targeting CCL19 with bamlanivimab did not make a difference compared to the placebo group." (PMID 35893822, 2022).
COVID-19 (continued). "Multiple studies show high levels of proinflammatory cytokines such as IL-1, TNF, IFNs, IL-6, IL-8, IL-18, IL-17α, G-CSF, and GM-CSF, as well as chemokines, such as MCP-1, IP-10, MIP-1α, CXCL10, CCL2, CCL4, CCL14, CCL19, and CCL25 in severe cases of COVID-19." (PMID 40076291, 2025). "In particular, CCL19 and CCL21 have been emphasized as markers of immune dysregulation in COVID-19, potentially indicating abnormal regulation induced by tissue inflammation." (PMID 40362649, 2025). "CCL-19, CCL-22, and CXCL-17 are also frequently raised in acute COVID-19 cases and are involved in T-cell, dendritic cell, and macrophage chemotaxis." (PMID 39000027, 2024). "Compared with age-matched unexposed elderly individuals, convalescent COVID-19 patients presented with more IFN-γ and less IL-7, while IL-2, IL-6, IL-10, IL-12p70, IL-33 and CCL19/MIP-3 were unchanged." (PMID 38424104, 2024). "While responses were not different between bamlanivimab- treated individuals and those who received placebo, CCL2, CCL19, CCL20, CXCL8 and CXCL10 were upregulated in samples from the nasopharyngeal cavity and the circulating blood of patients with COVID-19." (PMID 35303909, 2022). "Additionally, CCL19 serum levels were increased in patients with mild, moderate, and critical COVID-19 relative to healthy controls, and the treatment of patients with COVID-19 with baricitinib resulted in decreased CLL19 expression, suggesting that CCL19 may contribute to the severity of COVID-19." (PMID 35893822, 2022). "Among these, we pointed out a defined cytokine trait (CCL-12/MCP-5, CCL-19/MIP-3β, CXCL-2/MIP-2, etc.)of severe COVID-19 outcome." (PMID 34341347, 2021). "Interestingly, the two patients that died in hospital in our cohort had higher levels of CCL19 and PGF compared to the rest in the severe COVID-19 group." (PMID 39767799, 2024). "While some genes involved in monocyte and lymphocyte migration and function were expressed in the COVID-19(+) TV group (CCL13, CCL8, and CCL20), a greater number of these genes were expressed in the COVID-19(-) PU control group (CCL19, CCL18, CXCL13, CCL4, CCL5, CXCL9)." (PMID 37026002, 2023). "PIMS-TS children had significantly elevated levels of cytokines, IFNγ, IL-2, TNFα, IL-1α, IFNα, IFNβ, IL-6, IL-15, IL-17A, GM-CSF, IL-10, IL-33 and IL-Ra; elevated chemokines, CCL2, CCL19, CCL20 and CXCL10 and elevated VEGF, Granzyme B and PDL-1 in comparison to COVID-19, seropositive and controls." (PMID 33813138, 2021). "The MCODE plugin in Metascape was used to determine important modules and related hub genes in the constructed PPI network, and chemokines such as CCR1, CCL19, CXCL10, and CXCL16 were identified to present the most obvious changes in COVID-19 disease progression." (PMID 33195212, 2020). "In our study, we first showed that despite similar respiratory severity, plasma concentrations of numerous cytokines characterizing the “cytokine storm” (i.e. IL-1β, IL-6, IL-8, IL-15, TNF-α, CCL2, CCL4, CCL19, CCL20, TGF-α) were lower in COVID-19 compared to non-COVID-19 patients." (PMID 33272291, 2020). "And the subsequent PPI analysis results in our study also confirmed that chemokines related to inflammatory responses, such as CCR1, CCL19, and CXCL10, and the immune response-related gene FPR1 presented significant expression changes in the progression of COVID-19." (PMID 33195212, 2020). "Antibodies to the three chemokines with P < 10−4 (CCL19, CCL22 and CXCL17) clustered together and by themselves were sufficient to correctly assign healthy controls and COVID-19 convalescents with high accuracy (96.8%), so they were defined as a ‘COVID-19 signature’." (PMID 36879067, 2023). "Moreover, CCL19 expression was significantly increased among other cytokines in the lung tissue sections of patients with COVID-19, suggesting that CLL19 may be involved in the pathology of COVID-19." (PMID 35893822, 2022).
COVID-19 (continued). "Conversely, and regardless of vaccination status, antibodies to CCL19, CCL8, CCL13, CCL16, CXCL7 and CX3CL1 significantly increased, those to CXCL17 remained generally stable and those to CCL22 followed variable kinetics at month 12 compared with month 6 in the COVID-19 convalescents." (PMID 36879067, 2023).
lung carcinoma (24 papers, 2006 to 2025). "Ccl19 is a potent chemoattractant for T cells, B cells, DC, and NK cells, and it has been linked to reduced tumor burden in lung cancer." (PMID 40674254, 2025). "As a potential immune stimulator, CCL19 has been observed to be increased in lung cancer, and an association between CCL19 expression and high TNM staging and vascular invasion was identified." (PMID 33228590, 2020). "There are also indications that CCL19 suppresses lung cancer, colorectal cancer, ovarian cancer, and gastric cancer." (PMID 41272580, 2025). "CCL19-expressing fibroblasts contribute to an antitumor phenotype in lung carcinoma by promoting the accumulation and cytotoxicity of CD8+ T cells." (PMID 38786066, 2024). "Research has demonstrated that CCL19-producing fibroblastic stromal cells can restrain lung carcinoma growth by promoting local antitumor T-cell responses." (PMID 39505867, 2024). "Dysregulation of CCL19 has been noted in several cancers, including colorectal, pancreatic, and lung cancers, where it has been considered a potential tumor biomarker for diagnosis and prognosis." (PMID 37944262, 2023). "Fibroblasts were a heterogeneous population, and a previous study revealed ADH1B + CAF mainly originated from the CCL19-expressing ADH1B+ cells specifically found in TLS25 in lung cancer." (PMID 37537219, 2023). "Other research revealed that tumor microenvironment cells, such as fibroblastic stromal cells, produce CCL19, which promote local antitumor T-cell responses and restrain the growth of lung carcinoma." (PMID 35160116, 2022). "CCL19 mRNA expression level was upregulated (RQ > 1) in 53% of lung cancer tissue samples and in 40% of macroscopically unchanged controls." (PMID 35160116, 2022). "Even CCL19, transcribed by fibroblasts, inhibits the growth of lung cancer by promoting local anti-tumor T cell response and CXCL11 is known to be used as an enhancer of vaccine-induced CD8+ T cellular immunity." (PMID 34283076, 2021). "Nevertheless, some other studies indicated that CCL19 can modulate anti-tumor responses in lung cancer and ovarian cancer." (PMID 30250188, 2018). "Utilising subcutaneous murine lung cancer models, we have previously shown that CCL19 promotes IFN-γ-dependent antitumour responses." (PMID 16598185, 2006). "We embarked on the current studies to determine the antitumour properties of CCL19 in a clinically relevant model of lung cancer in which bronchoalveolar carcinomas develop in an organ-specific manner." (PMID 16598185, 2006). "In this study, utilising a transgenic murine model of spontaneous lung cancer that more closely resembles human lung cancer, we demonstrate that CCL19 mediates potent antitumour responses in vivo leading to significant tumour reduction." (PMID 16598185, 2006). "The antitumour activity of CCL19 was determined in the spontaneous model for lung cancer by injecting recombinant CCL19 into the axillary lymph node region of the transgenic mice." (PMID 16598185, 2006). "Taken together, the current study indicates that CCL19 injected in the axillary lymph node region in the late-stage spontaneous lung cancer model leads to the generation of effective antitumour responses." (PMID 16598185, 2006). "The potent antitumour properties demonstrated in this model of spontaneous bronchoalveolar carcinoma provide a strong rationale for additional evaluation of CCL19 regulation of tumour immunity and its use in immunotherapy for lung cancer." (PMID 16598185, 2006). "Previous studies have shown that CCL19 may be used as a potential immune stimulant in immunotherapy for certain cancer types, including breast and lung cancers." (PMID 37841886, 2023). "Furthermore, the study performed in murine models of lung cancer demonstrated that local and systemic administration of CCL19 combined with IL-7 is beneficial as potent anti-cancer strategy by stimulation of the immune response." (PMID 35160116, 2022).
lung carcinoma (continued). "The discovery of the CC chemokine receptor 7 (CCR7) in the membrane of lung cancer cells suggests that it may be utilized to migrate along the gradient of C-C motif chemokine 19 (CCL19) and chemokine 21 (CCL21) towards the lymph node and subsequently cause lymph node metastasis." (PMID 35160116, 2022). "Conversely, also in lung cancer, CCR7/CCL19 can promote the upregulation of heparanase-1 in the TME, contributing to the migration and invasion of A549 tumor cells, and lymph node metastasis." (PMID 38786066, 2024). "Cochrane’s Q test did not provide evidence of heterogeneity between CCL14 (p = 0.916), CCL19 (p = 0.446), CCL20 (p = 0.130), CCL21 (p = 0.878), CCL27 (p = 0.762), CXCL9 (p = 0.340) and CXCL13 (p = 0.770) and lung cancer." (PMID 38075694, 2023). "On the other hand, cigarette smoking has been shown to increase blood and bronchoalveolar lavage fluid levels of the CCR7 ligands CCL19 and CCL21, thereby contributing to migration of lung cancer cells." (PMID 32961854, 2020). "It has been reported that CCL19 and CCR7 are able to inhibit metastasis in lung cancer and ovarian cancer." (PMID 30250188, 2018). "In addition, a recent study also identified that CCL19, CCL20, and CXCL13 are highly expressed in lung cancer, and subsequent co-expression of CCL20 receptor CCR6 in CAR-T increased cell migration and tumor killing." (PMID 34553036, 2021).
melanoma (22 papers, 2007 to 2025). A malignant, usually aggressive tumor composed of atypical, neoplastic melanocytes. "Recently, researches revealed that the overexpression of CCL19 in serum was associated with the progression of melanoma." (PMID 35550569, 2022). "In the autochthonous Amela-melanoma model, splenic reduction in CCL19 and CCL21 transcripts was associated with loss of gp38+ FRC, generating a phenotype similar to that of plt/plt mice with a defect in recruitment of naïve TL." (PMID 21811640, 2011). "A 12-chemokine gene expression signature including CCL2-5, CCL8, CCL18, CCL19, CCL21, CXCL9-11, and CXCL13 has been previously reported to serve as a predictor for the presence of TLS in melanoma specimens in association with improved OS." (PMID 37435077, 2023). "For example, mouse melanoma and ovarian cancer cells transfected respectively to express mouse CCL19 and then inoculated into C57BL/6 mice, showed significantly slower tumor growth compared with the control group without CCL19 expression." (PMID 35702353, 2022). "APOD (apolipoprotein D) and ABCA8 (ATP-binding cassette, sub-family A member 8) encode transporter proteins while PRAME (preferentially expressed antigen in melanoma) and CCL19 (chemokine ligand 19) genes are involved in immunoregulatory processes." (PMID 26961242, 2016). "Following treatment with CCL19-myc and the 4A6 antibody, the melanoma cell line A375 that expresses endogenous CCR7 was specifically stained using a secondary peroxidase-conjugated antibody." (PMID 24068998, 2013). "The roles of KCNE4 in chemokine production and cell adhesion were examined using primary lymphatic endothelial cells, and demonstrated that Ccl17 and Ccl19, which are involved in melanoma metastasis, were upregulated by KCNE4, as well as Mmp3 matrix metalloproteinase." (PMID 35915077, 2022). "Previous studies indicated that CCL19 greatly participated in cancer cell proliferation, angiogenesis, migration, invasion and immune cell infiltration in multiple cancers, including gastric cancer, colorectal cancer, non-small cell lung cancer, lymphoma and melanoma." (PMID 35550569, 2022). "For example, treatment of melanoma with the STING agonist ADU S-100 increased the production of several TLS-inducible factors, such as CCL19, CCL21, Lt-α, Lt-β, and Light, and inhibited melanoma growth." (PMID 40038799, 2025). "For other chemokines, most of them tended to express higher in FGFR Mut melanoma, such as CCL5, CCL19, CXCL9, CXCL10, CXCL11, CXCL13 and CXCL14 (all P > 0.05)." (PMID 36426352, 2022). "Most chemokines were expressed intracellularly in all melanoma cell lines (CXCL9, CXCL11, CXCL12, CCL19, CCL21 and CCL27)." (PMID 24559071, 2014). "One group demonstrated that intratumoral injection of ADU S-100, a STING agonist, in a preclinical melanoma model promoted formation of CCL19+, CCL21+, PNAd+ TLS, although these TLS did not contain significant B cell infiltration or GCs." (PMID 38361928, 2024). "Our work revealed that serum level of APRIL/TNFSF13, but not CCL19, CXCL10 or CXCL13 when considered as single analytes, was associated with improved event-free survival (EFS) in patients with melanoma." (PMID 37435077, 2023). "In vitro, small extracellular vesicles from melanoma cells overexpressing wild-type nSMase2 enhance the expression of IL12, CXCL9, and CCL19 in bone marrow-derived dendritic cells, suggesting that melanoma nSMase2 triggers Th1 polarization at the earliest stages of the immune response." (PMID 35965565, 2022). "The mature adipocyte-stimulated expression of CCL19 and CCL21 in lymphatic endothelial cell, and expression of their receptor CCR7 in melanoma cells, which contributes to increased lymph node metastasis of melanoma in high-fat diet-fed mice." (PMID 29137230, 2017).